STAT3 (signal transducer and activator of transcription 3)
Diseases named in the same sentence as STAT3 in open-access papers (continued):
Sharing a sentence is not in itself a finding about the gene and the disease.
Zinc deficiency (7 papers, 2017 to 2025). A deficiency of the essential metal Zinc; an essential cofactor for many enzymes. "The ER Stress/CaMKII/STAT3 axis provides new therapeutic targets for the treatment of diseases caused by zinc deficiency." (PMID 35069232, 2021). "So it is possible that ER stress/STAT3 plays a role in regulating zinc transporter expression in response to cellular zinc deficiency." (PMID 35069232, 2021). "Zinc deficiency increased mRNA and protein expressions of the ER stress relevant markers Chop and Bip, and STAT3 phosphorylation in H9c2 or HL-1 cells, an effect that was abolished by ZnCl2." (PMID 35069232, 2021). "EGTA-AM also reversed TPEN or H/R-induced STAT3 phosphorylation, indicating that intracellular Ca2+ is responsible for zinc deficiency-induced STAT3 activation." (PMID 35069232, 2021). "Here we reveal that zinc deficiency activates STAT3 by ER stress-induced Ca2+ release and subsequent CaMKII activation, leading to enhancement of the transcriptional activity of the ZIP family zinc transporter genes." (PMID 35069232, 2021). "In conclusion, in this study, we demonstrated that zinc deficiency induced Ca2+ release can activate CaMKII at Thr286 which in turn leads to STAT3 activation." (PMID 35069232, 2021). "Zinc deficiency activates STAT3 by ER stress-induced Ca2+ release and subsequent CaMKII activation, leading to enhancement of the transcriptional activity of the ZIP family zinc transporter genes." (PMID 35069232, 2021). "Further studies showed that upregulation of STAT3 phosphorylation was reversed by Ca2+ chelator, indicating that intracellular Ca2+ is important for zinc deficiency-induced STAT3 activation." (PMID 35069232, 2021). "Since zinc deficiency can trigger both Ca2+ leak and STAT3 activation, it is possible that Ca2+ is involved in zinc deficiency-induced STAT3 activation." (PMID 35069232, 2021). "Further experimental data showed that zinc deficiency induced ER stress serves as an upstream signaling event leading to STAT3 activation and ZIP expression." (PMID 35069232, 2021). "Zinc deficiency increased IL-6-induced activation of JAK-STAT3 signaling pathways; reconstitution with zinc normalized the effect while zinc supplementation was shown to inhibit STAT3 phosphorylation induced by IL-6 and IL-1." (PMID 29064429, 2017). "Here, in vitro studies revealed that IL-4-induced STAT6 and IL-6-induced STAT3 phosphorylation were decreased during zinc deficiency." (PMID 29186856, 2017). "In this study, moderate zinc deficiency (1.5 μM) caused oxidative stress within 24 h, resulting in decreased tyrosine phosphorylation and retention of STAT3 in the cytosol." (PMID 29064429, 2017). "Moreover, B cell proliferation was increased during zinc deficiency, mediated amongst others by increased STAT3 phosphorylation." (PMID 36551176, 2022). "The present study investigated whether zinc deficiency induces leptin secretion by activating a JAK2/STAT3 signaling pathway and leads to osteoblastic apoptosis." (PMID 36615735, 2022). "Since STAT3 is activated upon zinc deficiency, it may play a role in the regulation of the Zip9 gene expression." (PMID 35069232, 2021). "Therefore, STAT3 activation linking to ZIP transporter expression in the setting of cellular zinc deficiency is a cellular adaptive mechanism by which cells attempt to homeostatically compensate for zinc loss." (PMID 35069232, 2021). "We next investigated whether the developmental impairment of the STAT3 signaling pathway caused by zinc deficiency could affect the number of astrocytes in the offspring brain cortex." (PMID 34049221, 2021). "To examine whether zinc deficiency could affect the interactions of STAT3 with JAK2 and the phosphatases PTP1B and SHP2, we immunoprecipitated STAT3 from E19 CT and did immunoblotting for the interacting proteins." (PMID 34049221, 2021).
Zinc deficiency (continued). "However, little is known on how developmental zinc deficiency can affect brain STAT3 activation during the period of active astrocyte generation and if this can have an impact on the adult brain astrocyte number and distribution." (PMID 34049221, 2021). "The deleterious effects of zinc deficiency on cytoskeleton assembly could affect the transport of active STAT3 from the cytosol into the nucleus." (PMID 34049221, 2021). "To test this hypothesis, we determined the effect of BAPTA-AM, an intracellular Ca2+ chelator, on zinc deficiency-induced STAT3 activation." (PMID 35069232, 2021). "Maternal zinc deficiency disrupted cortical STAT3 activation at E19 and P2." (PMID 34049221, 2021). "Taken together, results support the concept that an impairment of PTP1B degradation could be one of the mechanisms underlying zinc deficiency-mediated deactivation of the JAK2/STAT3 signaling pathway during early brain development." (PMID 34049221, 2021). "Moreover, zinc deficiency triggers the IL-6-induced phosphorylation of STAT3, thereby pathologically enhancing B cell differentiation into antibody-producing plasma cells and autoantibody production." (PMID 29186856, 2017). "Furthermore, zinc signals are important for IL-6 induced STAT3 phosphorylation shown to be increased due to zinc deficiency." (PMID 29064429, 2017). "Zinc deficiency caused B cell proliferation via increased STAT3 phosphorylation." (PMID 29186856, 2017). "In support, zinc deficiency enhanced ryanodine receptors (RyR), a channel in the ER that mediate Ca2+ release, and Ca2+-calmodulin-dependent protein kinase (CaMKII) phosphorylation, implying that zinc deficiency provoked Ca2+ leak from ER via RyR and p-CaMKII is involved in STAT3 activation." (PMID 35069232, 2021). "Thus, zinc deficiency-associated tubulin oxidation and depolymerization could affect the dynamics of the actin network and explain the observed decreased interaction of actin with STAT3 in the MZD brain cortex." (PMID 34049221, 2021). "TPEN or H/R can increase the release of LDH, while after KN93 treatment, the release of LDH further increased, indicating that inhibition of STAT3 activation can aggravate cell injury, since KN93 can reverse zinc deficiency induced STAT3 activation." (PMID 35069232, 2021). "Even zinc deficiency alone resulted in decreased phosphorylation of STAT3 and FLT3 in MV4‐11 and THP‐1 (data not shown)." (PMID 40583520, 2025). "Indeed, inhibition of CaMKII with KN-93, but not the inactive analog KN92, decreased zinc deficiency-induced STAT3 phosphorylation, pointing that CaMKII activation is vital to STAT3 activation." (PMID 35069232, 2021). "Moreover, inhibition of STAT3 activation blocked zinc deficiency induced ZIP9 expression, and resulted in increased Zn2+ loss in cardiomyocytes, further confirming that STAT3 activation during reperfusion promotes the expression of ZIP9 zinc transporter to correct the imbalance in zinc homeostasis." (PMID 35069232, 2021). "Besides, when STAT3 phosphorylation is inhibited by H89, KN93, BAPTA-AM, both the mRNA and protein expression of ZIP9 are decreased, further confirming that ER Ca2+ leak and CaMKII activation act as upstream signals respond to zinc deficiency to activate STAT3 and promote zip9 expression." (PMID 35069232, 2021).
adenovirus infection (6 papers, 2020 to 2026). "Adenovirus infection can cause inflammation and upregulation of the JAK/STAT pathway, ultimately leading to increased mRNA levels of IL-6, IL-1 β and IFN - α, as well as increased levels of JAK2, STAT3, p-JAK2 and p-STAT3 protein bands." (PMID 41399758, 2026).
alcoholic hepatitis (6 papers, 2020 to 2022). Acute hepatitis resulting from ingestion of alcohol. "All the main active components of lotus root can bind to STAT3, and inhibit binding to key sites on STAT3 can suppress the alcohol-induced inflammatory response and reduce the risk of alcoholic hepatitis." (PMID 36712522, 2022). "In summary, FAT10 was only found in human and mouse liver specimens and plays critical role in the development of alcoholic hepatitis via NFκB and/or STAT3 pathways induced by TNFα/IFNγ." (PMID 32630199, 2020). "The pathway that increases FAT10 expression includes TNFα and IFNγ, followed by NFκB and STAT3, all of which were up-regulated in alcoholic hepatitis." (PMID 32630199, 2020). "In alcoholic hepatitis, TNFα/IFNγ induces FAT10 expression via NFκB and/or STAT3 pathways." (PMID 32630199, 2020).
anaplastic astrocytoma (6 papers, 2009 to 2022). "Increased STAT3 activation, in the form of phosphorylated STAT3, was confirmed in GBM (grade IV), anaplastic astrocytoma (grade III), and diffuse astrocytoma (grade II)." (PMID 36046049, 2022). "Compared to healthy donors, patients with anaplastic astrocytoma (WHO grade III) and recurrent GBM (WHO grade IV) had statistically significantly higher levels of the percent of PBMCs displaying p-STAT-3." (PMID 19900287, 2009).
Anorexia (6 papers, 2019 to 2025). Lack of desire to eat (loss of appetite). "Altogether, these findings position STAT3 as a central node in the neuroimmune circuitry underlying cancer cachexia-associated anorexia." (PMID 40704145, 2025). "STAT3 has been associated with AN and the transmission of leptin signaling in previous studies using the activity-based anorexia (ABA) rat model." (PMID 38849516, 2024). "Knocking down HSP90 in HEK293 Ob-Rb cell line attenuates leptin-induced STAT3 signaling associated with anorexia." (PMID 38336777, 2024). "Our results revealed that SPX induces anorexia and leptin increases SPX expression via STAT3 signaling in the mouse hypothalamus, suggesting a possible role for SPX in the mediation of leptin’s anorexigenic effects in the hypothalamus." (PMID 35204737, 2022). "Targeting STAT3 or its regulatory partners, such as SOCS3, may offer a promising therapeutic strategy for alleviating anorexia and improving outcomes in cachectic patients." (PMID 40704145, 2025).
ataxia telangiectasia (6 papers, 2021 to 2025). Ataxia-telangiectasia is the association of severe combined immunodeficiency (affecting mainly the humoral immune response) with progressive cerebellar ataxia. "The study included five patients with X-linked agammaglobulinemia (XLA), four patients with Ataxia Telangiectasia (AT), and eight patients with various combined immunodeficiency (CID) diseases; STAT3 deficiency, CD40 ligand deficiency and IL6 receptor deficiency." (PMID 33557365, 2021).
autoimmune hepatitis (6 papers, 2021 to 2025). Hepatitis caused by autoantibodies. "Research has demonstrated that exosomes derived from bone marrow MSCs, enriched with miR‐223‐3p, can mitigate autoimmune hepatitis in mice by suppressing STAT3 and phosphorylated STAT3 (p‐STAT3) expression in LPS‐stimulated macrophages." (PMID 40859958, 2025). "In the case of autoimmune hepatitis, EGCG regulates the hepatic inflammatory microenvironment by inhibiting the NF-κB/STAT3 signaling axis and promotes a balanced state of autophagy and apoptosis to enhance the hepatocyte’s resistance to damage." (PMID 40218859, 2025). "Escin could protect against Con A-induced autoimmune hepatitis in mice via suppressing infiltration of neutrophils, CD4+ T cells, and monocytes into the liver, activation of Nrf2/HO-1 signaling pathway, inhibiting TNF-α/NF-κB, TNF-α/JNK, and IL-22/STAT3 signaling pathways." (PMID 36063304, 2022).
bile reflux (6 papers, 2020 to 2025). "In addition, an important role of STAT3 in bile-reflux-associated molecular oncogenic events has been demonstrated." (PMID 40872503, 2025). "We demonstrate that the administration of BAY 11-7082, either before or after acidic bile, eliminates NF-κB activation, prevents overexpression of Bcl2, Rela, Stat3, Egfr, Tnf, Wnt5a, and deregulations of miR-192, miR-504, linked to bile reflux-related hypopharyngeal cancer." (PMID 32934775, 2020). "Our novel data strongly support that STAT3 contributes substantially to bile reflux‐related molecular oncogenic events in HCs." (PMID 34850540, 2022). "STA‐21, SI3‐201 or Nifuroxazide effectively inhibited STAT3 and cancer‐related inflammatory phenotype, encouraging their single or combined application in preventive or therapeutic strategies of bile reflux‐related hypopharyngeal carcinogenesis." (PMID 34850540, 2022). "Our novel findings document the important role of STAT3 in bile reflux‐related molecular oncogenic events, which can be dramatically prevented by STAT3 silencing." (PMID 34850540, 2022). "Using three different inhibitors that each one can block a different step of STAT3 upstream signalling, we gained information that improve our knowledge regarding the mechanism of bile reflux‐related carcinogenesis in hypopharynx." (PMID 34850540, 2022). "Bile reflux can promote gastric carcinogenesis through the activation of the IL‐6/JAK1/STAT3 pathway and STAT3 inhibition can alleviate this carcinogenic effect." (PMID 35285172, 2022). "Moreover, bile reflux can promote GC by activating the IL-6/JAK1/STAT3 pro-inflammatory signal pathway, and inhibiting STAT3 can reduce this carcinogenic effect." (PMID 37719006, 2023). "Moreover, the bile reflux induced gastric precancerous lesions observed in the post BR surgery mice can be prevented by treatment with cryptotanshinone, a plant‐derived STAT3 inhibitor." (PMID 35285172, 2022). "Investigating whether STAT3 contributes substantially to BA‐induced molecular oncogenic profile may elucidate a better understanding to the mechanism of bile reflux‐related hypopharyngeal carcinogenesis and demonstrate useful key molecules for its early detection or targeted treatment." (PMID 34850540, 2022). "However, when the BR surgery with cryptotanshinone group was compared with the BR surgery group, the level of STAT3 phosphorylation was significantly decreased, indicating that cryptotanshinone had an offsetting effect on the activation of STAT3 induced by bile reflux." (PMID 35285172, 2022). "However, the role of STAT3 in bile reflux‐related hypopharyngeal carcinogenesis remains unclear." (PMID 34850540, 2022).
brain inflammation (6 papers, 2017 to 2024). "Mechanistically, SynHeps-II therapy ameliorated liver and brain inflammation caused by high levels of bilirubin and ammonia and promoted liver regeneration by modulating the nuclear factor κB (NF-κB) and signal transducer and activator of transcription 3 (STAT3) pathways." (PMID 39011520, 2024). "Taken together, these results suggest key roles of PGE2 autocrine and STAT3 in the severity of brain inflammation through up-regulation of MMP-9 in brain astrocytes." (PMID 33228717, 2020). "Altered IL-1β, IL-6, and TNF-α expression levels activating the STAT3 pathway have been found in brain inflammation models." (PMID 28143489, 2017).
bronchiectasis (6 papers, 2018 to 2025). Segmental, irreversible dilation of the bronchial tree resulting in the accumulation of secretions which leads to obstruction. "The hyper IgE syndrome with STAT3 dominant negative loss of function deficiency is another PID in which bronchiectasis is also frequently reported (37.5%)." (PMID 31801528, 2019). "Likewise, in Job’s syndrome, a disorder characterized by bronchiectasis, persistent lung infections, and increased IgE levels, a STAT3 gene mutation impairs IL-17 production, affecting the production of a diverse array of cytokines." (PMID 40589741, 2025). "Obviously, non-hematological disease manifestations (such as skeletal abnormalities in STAT3 DN) or irreversible remodeling processes (such as bronchiectasis/pneumatoceles in STAT3 DN or vascular changes in STAT1 GOF) cannot be successfully treated by HSCT." (PMID 37140667, 2023). "By mapping drug targets to disease targets, we identified 51 common targets, including IL10, TLR2, STAT3, IL6, and CXCL8, which served to indicate putative pathways whereby BMGLF could be used to treat bronchiectasis." (PMID 33488758, 2021).
chronic GVHD (6 papers, 2017 to 2023). "Past work from these authors also identified STAT3-dependent expansion and differentiation of pathogenic PSGLloCD4+ T cells in the lung and liver of recipients with chronic GVHD." (PMID 37526083, 2023). "In past work, these authors speculated that IL-6 and IL-21 could act upstream of STAT3 signaling in pathogenic CXCR5–PD-1hi helper T cells implicated in chronic GVHD pathogenesis." (PMID 37526083, 2023). "The differentiation of the PSGL1loCD4+ T helpers in chronic GVHD recipients depends on the IL-6R-Stat3-BCL6 pathway, and Stat3 or BCL6 deficiency in donor CD4+ T cells prevented expansion of the PSGL1loCD4+ T cells in GVHD target tissues." (PMID 34539630, 2021). "GVHD mortality: STAT3 ablation reduces posttransplant mortality as well as the severity of both acute and chronic GVHD, especially GVHD severity in the skin and colon." (PMID 28642760, 2017). "Prevention of PSGL1loCD4+ T expansion by BCL6 or Stat3 deficiency and by blockade of ICOS or PD-1 interaction with ICOSL or PD-L2 on B cells markedly reduced serum concentrations of autoantibodies and decreased the severity of chronic GVHD." (PMID 34539630, 2021). "Although our data indicate that targeting STAT3 in donor T cells can prevent acute GVHD while preserving GVL effect, whether targeting STAT3 in donor T cells could control established acute or chronic GVHD without inhibiting GVL activity is not yet known and should be addressed in future studies." (PMID 37526084, 2023).
chronic hepatitis (6 papers, 2016 to 2024). An active inflammatory process affecting the liver for more than six months. "HCC develops in the course of chronic hepatitis, which is associated with the continuous production of pro-inflammatory cytokines (TNF-α), which cause excessive activation of the STAT3 pathway, which promotes cancer development (positive feedback loop)." (PMID 39409068, 2024). "The genotype, allele and haplotype frequencies of the STAT3 rs1053004 and rs1053005 polymorphisms in HBV infection resolvers and patients with chronic hepatitis were compared." (PMID 29609539, 2018). "Compared to the unmanipulated HBV transgenic controls (#.282 and #.283), the mice with chronic hepatitis expressed higher levels of STAT3 protein in a Western blot analysis." (PMID 28968425, 2017).
chronic hepatitis B (6 papers, 2018 to 2025). "Xiao Cai Hu Tang (XCHT) is known as a TCM for liver treatment, particularly chronic hepatitis B. This TCM modulates STAT3 expression and indirectly suppresses the hepatitis B virus according to western blot analyses and real time PCR results." (PMID 33746739, 2020).
combined immunodeficiency (6 papers, 2014 to 2025). A broad classification of inherited disorders presenting at birth that affect both the cell-mediated and humoral aspects of the immune response. "Such diseases include CD25 or IL-2RA deficiency, mutations within STAT5b, STAT1 or STAT3, Dedicator of Cytokinesis 8 (DOCK8) deficiency as well as infantile or eosinophilic enteropathies and severe combined immunodeficiency (SCID)." (PMID 35207219, 2022).
craniosynostosis (6 papers, 2017 to 2021). Craniosynostosis is defined as the premature fusion of one or more cranial sutures leading to secondary distortion of skull shape resulting in skull deformities with a variable presentation. "However, the craniosynostosis and bone phenotypes seen in Il11RA1 deficient mice are not seen in Il11−/− mice, suggesting that developmental, STAT3-related bone effects are not due to defective IL11 signaling per se and instead, specific to Il11RA1 LOF." (PMID 34239012, 2021).